USP17L29 (ubiquitin specific peptidase 17 like family member 29)
Description:
Deubiquitinating enzyme that removes conjugated ubiquitin from specific proteins to regulate different cellular processes that may include cell proliferation, progression through the cell cycle, apoptosis, cell migration, and the cellular response to viral infection.
Target class: Enzyme; Hydrolase
Gene: Protein-coding gene on chromosome 4 (9,353,638 to 9,355,230, forward strand). Ensembl gene ENSG00000231637.
Subcellular location: Nucleus, nucleolus; Endoplasmic reticulum
Pathways (Reactome):
Metabolism of proteins: Ub-specific processing proteases
Gene Ontology:
Molecular function: cysteine-type deubiquitinase activity; hyaluronic acid binding; RNA binding
Biological process: positive regulation of epithelial cell apoptotic process; protein deubiquitination involved in ubiquitin-dependent protein catabolic process; regulation of apoptotic process; protein deubiquitination
Cellular component: nucleolus; nucleus; endoplasmic reticulum
Homologues: Paralogues in human: USP17L24 (100% identical), USP17L25 (100% identical), USP17L26 (100% identical), USP17L27 (100% identical), USP17L28 (100% identical), USP17L30 (100% identical), USP17L5 (99% identical), USP17L20 (99% identical), USP17L11 (99% identical), USP17L17 (99% identical), USP17L18 (99% identical), USP17L22 (99% identical), and 59 more.